KLF4 (KLF transcription factor 4)
Diseases named in the same sentence as KLF4 in open-access papers (continued):
Sharing a sentence is not in itself a finding about the gene and the disease.
tumor (continued). "Nevertheless, as relatively little is currently known about the effects of BLIMP1 and KLF4 expression on normal gastric cell and GC tumor cell differentiation, the ability of IRF6 to induce lytic EBV reactivation in GC tumors may also be mediated via additional (BLIMP1/KLF4-independent) mechanisms." (PMID 40569988, 2025). "Experimental data suggest that KLF4 may regulate the G1/S transition by modulating cyclin expression and interacting with key cell cycle regulators, such as p21, suggesting a complex role in tumor progression." (PMID 40299916, 2025). "Moreover, whether KLF4 itself is epigenetically regulated during immune priming, as in tumor development, or if it directly recruits chromatin-modifying complexes warrants further mechanistic investigation." (PMID 40552304, 2025). "It is not only highly mutated and overexpressed in tumor patients but also promotes the proliferation and metastasis of PCa through various mechanisms, including activation of the leukemia inhibitory factor receptor (LIFR), Kruppel-like factor-4 (KLF4) and antioxidant pathways." (PMID 41247636, 2025). "Additionally, KLF4 is closely related to macrophage polarization, regulating their polarization toward the pro-inflammatory M1 type or the anti-inflammatory M2 type and thereby affecting tumor immune escape and progression." (PMID 39995670, 2025). "Therefore, KLF4 is thought to function as a tumor suppressor in T‐ALL cells; however, its role in the differentiation of T‐ALL cells remains unclear." (PMID 40354086, 2025). "Moreover, KLF4 appears to exert a crucial role in both cancer cell stemness and tumor development." (PMID 40299916, 2025). "The interplay between KLF4 isoforms and chromatin-modifying enzymes within MDSCs warrants deeper investigation and may uncover new mechanisms of immune plasticity relevant to wound repair, fibrosis, and tumor progression." (PMID 40552304, 2025). "Thus, the downregulation of KLF4 may play a role in tumor proliferation by inducing β-catenin expression and activating Wnt/β-catenin signaling pathway." (PMID 38167453, 2024). "Interestingly, in terms of carcinogenesis, Klf4 may have dual functions as a tumor suppressor and oncogene, depending on the type of cancer." (PMID 38699229, 2024). "However, we still lack evidence that KLF4-driven senescent cells directly promote tumor migration." (PMID 38951874, 2024). "In NSCLC, KLF4 could be taken as an tumour suppressor with different types of upstream activator." (PMID 38924680, 2024). "KLF4 is a tumor suppressor, and KIF4 SNV may affect its DNA binding ability and apoptotic function." (PMID 38870270, 2024). "Notably, the depletion of GTSE1 leads to the upregulation of KLF4, a tumor suppressor in KIRC." (PMID 38464749, 2024). "Therefore, the lack of NANOG expression by MDA-MB-231 cells may have switched the oncogenic KLF4 to tumor suppressor mode, which consequently induced differentiation upon cisplatin and C. nutans treatment." (PMID 37250812, 2023). "Importantly, the higher the malignancy of tumor, the lower the expression of KLF4." (PMID 37031197, 2023). "We confirmed that KLF4 expression levels in HCC samples were significantly lower than in non-tumor tissues, and increased KLF4 expression was inversely correlated with advanced tumor grade and tumor stage, indicating that decreased KLF4 expression may promote the progression of HCC." (PMID 36936440, 2023). "Similarly, STAT3 activated the secretion of LCN2(lipocalin 2) from N2 neutrophils, which induced mesenchymal-epithelial transition of tumor cells via ERK/KLF4 signaling pathway and thereby facilitating colonization and metastatic outgrowth in lung under the circumstance of nicotine." (PMID 35356244, 2022).
tumor (continued). "However, the antifibrotic effect of KLF4 in skin HS remains elusive." (PMID 35637963, 2022). "WISP2 has a role in tumor susceptibility through EMT via the TGF-β signaling pathway, KLF4 expression, and miR-7 inhibition, thus proposing WISP2 as an activator of CTL-induced death and suggesting that the loss of its function promotes immune surveillance evasion and tumor promotion." (PMID 36012357, 2022). "Interestingly, deguelin could significantly promote the expression of KLF4 in cell lines and mouse tumor tissue of NSCLC to play an important antitumor role." (PMID 35637651, 2022). "In addition, KLF4 includes deactivation and transcriptional inhibition domains in N-terminal, it exerts an oncogenic or tumor repressive role by functioning with multiple target genes in various tumor tissues." (PMID 35027543, 2022). "However, KLF4 can also act as a tumor suppressor in a context-dependent manner." (PMID 33918002, 2021). "Interestingly, KLF4 has been previously considered as tumor suppressor in several studies." (PMID 33882454, 2021). "Thus, a deeper understanding of the roles of KLF4 in tumor progression is needed." (PMID 34680284, 2021). "However, in many human cancers, KLF4 is regarded as a tumor suppressor." (PMID 33917010, 2021). "However, this hypothesis is challenged by current finding, which demonstrated consistent roles of KLF4 as a tumour suppressor and differentiation inducer in HCC cases." (PMID 34114341, 2021). "Finally, Klf4 and Egr1 levels were lower in the CTCs containing Parsortix-isolated samples, while Dusp10 and Pmepa1 higher levels in these samples could indicate tumor presence." (PMID 35153760, 2021). "Moreover, the staining results of immunohistochemistry (IHC) showed that KLF4 expression is predominantly decreased in tumor tissues, and lower KLF4 expression was associated with poorer prognosis of HCC patients, which indicated that KLF4 potentially acts as a prognostic marker for HCC patients." (PMID 32756012, 2020). "Thereby, we regarded KLF4 as a tumor suppressor that could inhibit HCC progression." (PMID 32756012, 2020). "In this way KLF4 suppresses oncogenic transforming growth factor beta (TGF-β) signaling, and therefore loss of KLF4 expression in primary HCC cells may contribute towards the activation of oncogenic TGF-β signaling and subsequent tumor progression." (PMID 33266506, 2020). "By siRNA targeting of KLF9 in Ishikawa cells to mimic the low levels found in EC tumors, we found that MET may compensate for the progressive loss of KLF9 in tumor cells by rapidly increasing transcript levels for PGR, PGR-B, and KLF4, all of which exhibit anti-tumor properties." (PMID 32046384, 2020). "Interestingly, we also observed that KLF4 expression negatively correlated with vascular invasion, suggesting KLF4 may inhibit the tumor growth of HCC by regulating angiogenesis." (PMID 32756012, 2020). "KLF4 is a potential novel tumor suppressor in NSCLC and may be a promising therapeutic target." (PMID 31969824, 2019). "Ectopic expression of KLF4 has been reported to suppress cell proliferation, induce apoptosis, and promote cell-cycle arrest, indicating that KLF4 has a tumour suppressor function in a variety of malignancies and that its downregulation may play an essential role in tumourigenesis." (PMID 30658712, 2019). "Ectopic expression of KLF4 has been reported to suppress cell proliferation, induce apoptosis, and promote cell-cycle arrest, indicating that KLF4 has a tumour suppressor function in a variety of malignancies and its downregulation may play an essential role in tumourigenesis." (PMID 30176890, 2018). "In addition to changing tumor cell intrinsic properties, the KLF4-miR-182 cluster axis could contribute to tumor progression by altering the metastatic niche." (PMID 28412746, 2017). "In addition, KLF4 could directly interact with Wnt/β-catenin signaling to suppress Wnt signaling and inhibit tumor growth." (PMID 27153563, 2016).
tumor (continued). "Still, a significant increase of the KLF4α/KLF4(FL) ratio in the tumor could be determined." (PMID 27323810, 2016). "However, it is reasonable to hypothesize that not the loss of KLF4(FL) per se is tumorigenic, but that a potential resulting increase of KLF4α/KLF4(FL) ratio might stimulate tumor growth." (PMID 27323810, 2016). "Furthermore, it is demonstrated that KLF4 can regulate sprouting angiogenesis and may be a therapeutic target in regulation of tumor angiogenesis." (PMID 26823670, 2016). "In addition, we found that ITLN1 induced the KLF4 expression via inactivation of PI3K/AKT signaling, which was required for ITLN1-mediated up-regulation of NDRG2 in NB cells, suggesting the tumor suppressive roles of ITLN1/KLF4/NDRG2 axis in the tumorigenesis of NB." (PMID 25889839, 2015). "Interestingly, in contrast to its role as a tumor suppressor, in many cancer types KLF4 may act as an oncogene in a context dependent manner, as it is overexpressed in primary breast ductal carcinoma and oral squamous cell carcinoma." (PMID 25944097, 2015). "In addition, KLF4 plays an important role in T cell development and differentiation by controlling T cell number and its function on tumor microenvironment is still unknown." (PMID 26517087, 2015). "However, we do not make any conclusion regarding the function of ST18 as a tumor suppressor or oncogene outside of the liver and draw attention in this matter to KLF4, a transcriptional repressor known to function as a tumor suppressor and as an oncogene, depending on context." (PMID 23540693, 2013). "In addition, KLF4 is a stem cell marker that promotes cancer stem cell population maintenance and CD59 upregulation may be associated with tumor cell immune escape." (PMID 22900095, 2012). "This suggests that KLF4 may function as a tumor suppressor in RCC." (PMID 21982273, 2011). "Furthermore, our data from hESC-derived NSCs indicate that reprogramming can be achieved without ectopic expression of the tumor-associated genes, c-Myc and Klf4." (PMID 19763270, 2009). "For example, in macrophages, KLF4 drives M1/M2 polarization via cooperation with STAT6 and suppression of NF‐κB signaling, thereby shaping the landscape of tumor immune evasion." (PMID 41532367, 2026). "This direct link between APTO253‐driven KLF4/MICA induction and enhanced NK cell‐mediated clearance reveals a novel therapeutic axis, offering a promising strategy to restore anti‐tumor immunity in AML." (PMID 41532367, 2026). "We summarize how differential KLF4 expression in various TME cell types impacts immune regulation, ECM remodeling, and tumor progression, and discuss the therapeutic potential and current challenges of strategies targeting KLF4–TME interactions." (PMID 41532367, 2026). "Forced expression of KLF4 can promote the differentiation of CD8+ T cells toward the transient effector subset, enhance their anti‐tumor effector functions, and possess the potential to reverse CD8+ T cell exhaustion." (PMID 41532367, 2026). "The following discussion will focus on how KLF4 expression influences the abundance or activity of specific cell types within the TME, and how these changes, in turn, affect tumor progression." (PMID 41532367, 2026). "KLF4 upregulation combined with Notch3, HER3, and p-Smad2 downregulation disintegrated the regulatory network of tumor stemness from multiple dimensions." (PMID 40438682, 2025). "Increasing evidence supports the dual functionality of specific genes, including KLF4, PSME2, and TGF-β, as both oncogenes and tumor suppressors, depending on cancer type and stage." (PMID 41235100, 2025). "Western blot analysis of tumor tissues revealed elevated expression of CD133, CD15, Nestin, Sox2, and Klf4 in mice implanted with CD133−CD15− cells treated with TMZ compared to controls without TMZ treatment." (PMID 40253386, 2025).
tumor (continued). "Specifically, hepatocytes at the tumor periphery predominantly expressed TFs such as ILF2, ATF7, and RFXANK, while those in the tumor core were enriched for KLF4, EGR1, and HES5." (PMID 40474968, 2025). "Results of this research showed that KLF4 was significantly downregulated in SCCE and act as a tumor suppressor." (PMID 39944135, 2025). "Gene expression profiling plays a crucial role in understanding the role of Krüppel-like factor 4 (KLF4) in the prognosis and tumor immune microenvironment of various malignancies." (PMID 40299916, 2025). "Studies have indicated that in HCC patients with high KLF4 expression, the tumor immune microenvironment (TIME) is characterized by increased CD8+ T cell infiltration, suggesting a potential correlation between KLF4 expression and CD8+ T cell infiltration." (PMID 39995670, 2025). "The overexpression of miR-29a led to an arrest of tumor initiation and a decrease in CSCs in TNBC by directly targeting KLF4." (PMID 40863723, 2025). "Our studies identify the IFN-γ-KLF4-SLURP1 and CD200-CD200R1 axes as critical molecular drivers in tumor dormancy regulated by immune-tumor crosstalk." (PMID 40568095, 2025). "In accord with these findings, both KLF4 and SLURP1 were increased in 4T1 and D2A1 tumor cells upon treatment with IFN-γ." (PMID 40568095, 2025). "In tumor-specific CD8+ T cells, high KLF4 expression upregulates AP-1 family factors, such as c-Jun, conferring transient effector characteristics upon CD8+ T cells." (PMID 39995670, 2025). "The increased levels of miR-10b lead to suppression of Krüppel-like factor 4 (KLF4), a tumor suppressor and transcription factor involved in the maintenance of epithelial cell differentiation and inhibition of epithelial-to-mesenchymal transition (EMT)." (PMID 40116906, 2025). "A study have highlighted, in melanoma nodal metastases, the existence of two distinct subpopulations of cells simultaneously expressing OCT4, SOX2, KLF4, and c-MYC markers—one located in the tumor nests and the other in the peritumoral stroma." (PMID 40806546, 2025). "Its overexpression resulted in decreased Krüppel-like factor 4 (KLF4) levels and the marked suppression of tumor cell proliferation and invasion, and it induced apoptosis in the LSCC cell line Hep-2." (PMID 39941323, 2025). "KLF4 was consistently downregulated across all HCC groups and in untreated chronic HCV patients (p < 0.0001), supporting its potential tumor-suppressive role." (PMID 41386849, 2025). "Low levels of KLF4, c-MYC, and NANOG and high expressions of SOX2 and OCT4 in tumor tissue correlated with poor overall survival (OS) and disease-free survival (DFS), respectively." (PMID 41463190, 2025). "IFN-γ in turn elevated KLF4-mediated SLURP1 production in malignant cells, which is critical to the tumor cell quiescent state through interruption of fibronectin-integrin signaling pathways." (PMID 40568095, 2025). "GW9662 exhibits the ability to suppress stem cell-related genes (KLF4 and ALDH), leading to apoptosis induction and inhibition of tumor sphere formation." (PMID 40303293, 2025). "KLF4 plays an important role in regulating the differentiation and function of CD8+ T cells, influencing their ability to recognize and kill tumor cells." (PMID 39995670, 2025). "BIN1 overexpression correlated with reduced expression of key stemness and EMT markers, including Myc, ALDH1, OCT4, EPCAM, KLF4, NANOG, SOX2, and decreased tumor sphere-formation capabilities, suggesting EMT inhibition." (PMID 40016843, 2025). "In tumor-specific CD8+ T cells, KLF4 enhances effector function by regulating the expression of AP-1 family factors, such as c-Jun, thereby counteracting terminal exhaustion." (PMID 39995670, 2025). "The results showed that the expression of KLF4, p-JAK1, and p-STAT6 was increased in the tumor tissue of the sleep deprivation group compared to the normal sleep group." (PMID 40276761, 2025).
tumor (continued). "Conversely, upon administration of ADRB2 blockers, the expression level of KLF4, p-JAK1, and p-STAT6 was reduced, along with a decrease in the proportion of pro-tumoral macrophages in the tumor microenvironment." (PMID 40276761, 2025). "Herein, several KLF4-assocaited genes, C10orf54 and CD274 were correlated with tumor suppression, while others, including CX3CL1, TNFRSF4, and IL1A, were correlated with tumor stimulation." (PMID 40299916, 2025). "Recent in vivo interaction screening studies have demonstrated that plexin B2 expressed by hepatocytes interacts with class IV semaphorins on tumor cells, leading to the upregulation of KLF4, which subsequently promote MET and facilitates tumor metastasis." (PMID 41415713, 2025). "The expression of chemoresistance genes has been detected, including KLF4 (doxorubicin and ifosfamide), ULK1, LUM, GPNMB, and CAVIN1 (doxorubicin), and AHNAK2 (gemcitabine) in tumor cells and ETS1 (gemcitabine) in TME." (PMID 39685635, 2024). "In the embryonic stem cell subnucleus, KLF2 and KLF4 co-localize with OCT4, and KLF-DNA binding dynamics occur during differentiation for direct regulation of stem cell genes and tumor neovascularization." (PMID 38560274, 2024). "GHRL, KLF4, and DUSP5 expression levels were relatively lower in tumor tissues, whereas DSP, PERP, and MMP9 were highly expressed in tumor tissues." (PMID 38273348, 2024). "Additinally, the knockdown of KLF4 in the SW480 CRC cell line induced the YAP pathway and its downstream genes, including EGFR, MYC, BIRC5, and CTGF, leading to tumor proliferation." (PMID 38167453, 2024). "A decrease of KLF4 was observed in the NSCLC tissues and metastatic tumour tissues located in the trachea and main bronchus." (PMID 38924680, 2024). "Research indicates that miR-145 exerts anti-stemness and tumor inhibitory effects by directly targeting OCT4, NANOG, SOX2 and KLF4, conversely, these pluripotent TFs can also induce or inhibit the transcription of diverse miRNAs." (PMID 38561775, 2024). "We demonstrated a significant inhibitory effect of KLF4 on HCC proliferation both in vitro and in vivo, highlighting its potential tumor-suppressive role in HCC development." (PMID 39000273, 2024). "Napabucasin downregulates stemness-related genes Nanog, SOX2, Klf4, and Oct4 CD90 and EpCAM mRNA expression levels both in tumor cells and tumor tissues." (PMID 37570646, 2023). "KLF4 is a Yamanaka factor important for pluripotency, while SMAD3 is essential for TGFB1 signaling, and PPARG has complex roles in tumor metabolism and immunity; they have known roles as positive and negative regulators of EMT and bladder carcinogenesis." (PMID 38129585, 2023). "In addition, a tumor-burden mice model by cell transplantation further demonstrated the promotion of tumor growth by pMX-CCAT2 in vivo, which was associated with increased levels of cell proliferation factors (Ki67 and CCND1) and cell stemness genes (h-TERT, NANOG, SOX2, KLF4 and OCT4)." (PMID 36672487, 2023). "KLF4 also regulates TGF-β, Notch-1 and P57, affecting the tumor proliferation, differentiation and apoptosis." (PMID 37031197, 2023). "Curiously, depending on the disease stage, as in the case of KLF4 and KLF5, their role can switch between oncogene and tumor suppressor." (PMID 37239940, 2023). "By monitoring the tumor burden by GFP-positive area within each lung slice, we saw that knocking out KLF4 decreased the ability of the cells to grow within the context of the metastatic microenvironment." (PMID 37938582, 2023). "Conversely, knocking down KLF4 resulted in an increase in Ki67, PITX1, and SOX2 expression levels, and an increase in the malignancy of tumor tissue." (PMID 37841446, 2023). "GTSE1 works by regulating the expression of Krüppel-like factor 4 (KLF4), which is a tumor suppressor." (PMID 37370817, 2023).